STAT3 (signal transducer and activator of transcription 3)
Diseases named in the same sentence as STAT3 in open-access papers (continued):
Sharing a sentence is not in itself a finding about the gene and the disease.
cancer (continued). "STAT3 phosphorylation is usually abnormally activated in malignant tumors and is associated with poor clinical prognosis and many biological processes, especially cell differentiation, proliferation, and invasion." (PMID 36769245, 2023). "Activation of the STAT3 signaling pathway is associated with cancer cell survival, proliferation, immunosuppression, angiogenesis, invasion, and metastases, among other tumorigenic processes 7-10." (PMID 37928418, 2023). "In breast cancer, it has also been observed that interlukin -6 (IL-6), secreted by breast cancer-associated MSCs, protected cancer cells from cisplatin-induced apoptosis by activating the signal transducer and activator of the transcription 3 (STAT3) pathway." (PMID 37175439, 2023). "While Mito-STAT3 augmented ATP production and reduced ROS production, Mito-STAT3 deficiency reduced mitochondrial ATP (Mito-ATP) production and increased Mito-ROS production, leading to apoptosis in certain cancer cells." (PMID 37526084, 2023). "In patients with advanced cancer, cachexia usually occurs through two proteolytic signaling pathways activated by p-Stat3 in the muscle, causing muscle wasting or loss." (PMID 37375942, 2023). "Other investigators have reported similar findings, showing that STAT3 has been linked to EGFR, where EGFR can activate STAT3, thus contributing to cancer progression." (PMID 36977736, 2023). "STAT3 was identified as an acute-phase response factor that is linked with cancer and other diseases." (PMID 37978263, 2023). "The association of STAT3 with tumorigenesis and immune functions has been extensively investigated in numerous cancers for decades." (PMID 37121974, 2023). "The administration of withaferin A in Caki cancer cells caused a marked downregulation of STAT3 activation and a decrease in the expression of various STAT3-regulated genes." (PMID 37259311, 2023). "In TNBC patients, high expression of stromal STAT3 was associated with reduced cancer‐specific survival (HR = 2.202, 95% CI: 1.148–4.224, log rank p = 0.018)." (PMID 37199043, 2023). "Upon activation, STAT3 relocates to the nucleus, where it modulates the expression of genes linked to the proliferation, invasion, and resistance to chemotherapy in cancer cells." (PMID 37894443, 2023). "Several reports highlight the role of IL-6 trans-signaling and activation of the STAT3 pathway in mediating an exaggerated activation of fibroblasts leading to their transformation into cancer-associated fibroblasts." (PMID 37049615, 2023). "Activator of transcription 3 (STAT3) plays a significant role in the progression of cancer cells and cancer-associated DCs." (PMID 38004600, 2023). "The signaling pathways leading to CAC predominantly target the NF-κB, PI3K/AKT, and STAT3 pathways, which are critically associated with both inflammation and cancer." (PMID 38288125, 2023). "Several reports showed that IL-6 and p-STAT3 levels were associated with poor clinical prognosis in several kinds of cancer." (PMID 36635302, 2023). "CSF2 is linked to the promotion of cancer stem cells via the activation of STAT3 and myeloid-derived suppressor cells." (PMID 36980301, 2023). "Signal transducer and activator of transcription 3 (STAT3) is an oncogenic transcription factor that has been implicated in many human cancers and has emerged as a target for cancer therapy." (PMID 36916296, 2023). "RUNX1 appears to be essential for solid tumor initiation and maintenance through upstream stimulation of STAT3 signaling, a central cancer pathway associated with a variety of cancer diseases." (PMID 37760803, 2023). "In the TIMER database, the same results across the algorithms showed that the expression of STAT3 and cancer-associated fibroblasts showed an inverse correlation in ESCA (P < 0.05)." (PMID 36977736, 2023). "Elevated activity of signal transducer and activator of transcription 3 (STAT3) is evident in numerous cancers and plays a pivotal role in inflammation-associated tumorigenesis." (PMID 38023173, 2023).
cancer (continued). "The antitumor activities of ginsenoside have been previously linked to the selective inhibition of Stat3 phosphorylation in cancer cells." (PMID 37092860, 2023). "HERC2 enhanced the stemness and PD-L1-mediated immune evasion of HCC cells, which is associated with the activation of signal transducer and activator of transcription 3 (STAT3) pathway during the inflammation-cancer transition." (PMID 36721234, 2023). "At the same time, high levels of miR-221-3p in OS cells are associated with JAT/STAT3 activation, migration, invasion, and high viability of cancer cells." (PMID 37240338, 2023). "Despite the aberrant activation of STAT3 signaling being associated with inflammatory processes and cancer, STAT3 is critical in maintaining cellular homeostasis rather than playing a singular role in acute phase responses." (PMID 37049615, 2023). "HDACis inhibit the activity of cancer stem cells by targeting several essential genes involved in cancer stem cell maintenance, such as those encoding β, γ-catenin, Stat3, and Notch1, thereby reducing tumor development." (PMID 36810560, 2023). "miR-16-5p and 20b-5p were found to be associated with STAT3 (Signal Transducer and Activator of Transcription 3), a gene related to pathways in cancer." (PMID 37374977, 2023). "Our results show that ROR1 and its downstream STAT3 are co-expressed in epithelial as well as stromal cells of OC tumors, including cancer-associated fibroblasts or CAFs." (PMID 37400436, 2023). "STAT3 play critical roles within neoplastic cells, immune cells, and other stromal cells, such as cancer-associated fibroblasts (CAFs)." (PMID 36902166, 2023). "Since membrane HLA-G expression is linked with STAT3 activation in cancer cells, we chose the membrane localizing SPAG9 protein from the candidate HLA-G protein partners for further investigation." (PMID 36780531, 2023). "Since a major cause of chemoresistance is cancer stemness, it is as expected that canonical STAT3 signal transduction pathways play an essential role in cancer stem cell-associated chemoresistance." (PMID 37642779, 2023). "While constitutive activation of STAT3 is linked to cancer cell proliferation and survival, enhanced proliferation of mouse and human cells is promoted by inhibition or knockdown of STAT3 activity in vitro and in vivo." (PMID 37143896, 2023). "In particular, it was demonstrated that in patients with GC, increased p-STAT3 expression is predictive of poor prognosis because it is functionally associated with worst cancer differentiation and positive lymph node metastasis." (PMID 36979673, 2023). "It is considered as a key cytokine effecting STAT3 phosphorylation in many cancers, and it is associated with a poor prognosis." (PMID 38201482, 2023). "Extraction of previously uncharacterized perturbed subnetworks allowed us to detect other cellular processes implicitly associated with TOMM34 including NOTCH-, MAPK-, and STAT3 signaling, frequently deregulated in cancers." (PMID 36829477, 2023). "Simultaneously, IL-6/STAT3 signaling in malignant EMT leads to the acquisition of cancer stemness in cancer cells; self-renewal and population expansion of CSCs need STAT3 in collaboration with stem-cell-associated transcription factors." (PMID 37373393, 2023). "The Janus kinase (JAK) and signal transducer and activator of transcription 3 (STAT3) signaling pathway is aberrantly hyperactivated in many types of cancer, and such hyperactivation is generally associated with a poor clinical prognosis." (PMID 37103357, 2023).
cancer (continued). "Inflammation and cancer are linked through relevant external environments with intrinsic pathways, and STAT3 is a major intrinsic pathway linking inflammation and cancer." (PMID 36995541, 2023). "Studies have shown that HECT domain and RCC1-like domain 2 (HERC2) enhance cancer stemness and PD-L1-mediated immune escape of HCC cells, which is associated with activation of the STAT3 pathway during the inflammation-cancer transformation." (PMID 38155974, 2023). "It has been demonstrated that FTY720 blocks the SPHK1/S1P/S1PR1 axis, leading to the blockade of the NF-kB/IL-6/STAT3 amplification loop and colitis-associated cancer." (PMID 36714534, 2023). "A recent study demonstrated a significant correlation between STAT3 and mTOR overexpression, which underlies cancer-mediated drug resistance and cancer progression." (PMID 37446140, 2023). "The present study aimed to investigate the role of activated STAT3 in promoting MB pathogenesis and chemoresistance via inducing the cancer hallmark MYC oncogene." (PMID 37190167, 2023). "Continuous activation of JAK2/STAT3 signaling pathway is often associated with the proliferation, invasion, metastasis and other behaviors of malignant tumors, which is also the focus of research on JAK/STAT signaling pathway." (PMID 37575547, 2023). "The results showed that in HNSCC, increased levels of circRNA FAT1 regulated the positive association between immune evasion and cancer stemness by promoting the activation of STAT3." (PMID 36894542, 2023). "Activation of STAT3 is an important hallmark as it contributes to the initiation and progression of cancer, which enhances cell proliferation, migration, invasion, and angiogenesis through transcriptional regulation." (PMID 37095578, 2023). "JAK2/STAT3 signaling activates epiregulin-induced cancer-associated fibroblasts, which stimulates the epithelial–mesenchymal transition (EMT) of OSCC cells, which is necessary for migration and invasion." (PMID 38259290, 2023). "Activation of the STAT3 signaling pathway has been implicated in the development of numerous human cancers." (PMID 37161425, 2023). "Its anti-cancer effect is strongly associated with the inactivation of the signal transducer and activator of transcription 3 (STAT3)." (PMID 35890129, 2022). "STAT-3 signaling serves a key role in cancer as it is associated with increased proliferative, migratory, invasive and metastatic capacity." (PMID 35703345, 2022). "The signaling pathway with phosphorylation of JAK2/STAT3 is associated with the management and enhancement of cancer cell proliferation, as well as resistance to radiation therapy that is one of the key roles of STAT signaling." (PMID 36193062, 2022). "Some of the STAT3-associated signaling pathways have been reported in some hematological malignancies and solid tumors and in facilitation of cancer proliferation via regulation of CSC activities." (PMID 36061200, 2022). "Many cellular responses involved in cancer have been implicated to interact with the signal transducer and activator of transcription 3 (STAT3) protein, a transcription factor known to mediate cytokine signalling." (PMID 35903542, 2022). "Activation of the JAK2/STAT3 pathway can promote cell survival and proliferation, inhibit apoptosis, and is implicated in the occurrence and development of various cancers." (PMID 35116094, 2022). "IL-6/JAK/STAT3 signaling pathway is abnormally hyperactivated in various cancers, and is associated with poor prognosis." (PMID 35090515, 2022). "Among the cytokines linked to inflammation-associated cancer, IL-6 drives many cancer hallmarks through the downstream activation of the STAT3 (Signal transducer and activator of transcription 3) signaling pathway." (PMID 36547079, 2022).
cancer (continued). "LncRNA-MALAT1 exerts a functional role in the cancer development as well as the drug resistance and is linked with STAT3 activation and activity of FUT4." (PMID 35281907, 2022). "Signal Transducer and Activator of Transcription-3 (STAT3) has been strongly implicated in many cancers, and its constitutive activation promotes growth, angiogenesis, inflammation, and immune evasion." (PMID 35401187, 2022). "The results showed that IFN‐γ produced by TAMs enhances the constitutive activation of STAT3 in cancer cells, which is associated with PD‐L1 expression." (PMID 35356799, 2022). "These clues provided impressive evidence that betulinic acid not only interfered with STAT3-mediated signaling but also downregulated metastasis associated proteins to inhibit the spread of metastatic spread of cancer cells." (PMID 36615262, 2022). "In cancer tissues, the unlocking of the phenotypic plasticity of cancer cells concurs with EMT, and the EMT‐related regulators including STAT3 are associated with cancer cell dedifferentiation." (PMID 35356799, 2022). "The continuous activation of STAT3 regulates the expression of downstream proteins associated with the formation, progression, and metastasis of cancers." (PMID 35356799, 2022). "Phosphorylated STATs can trigger the expression of genes involved in inflammatory responses and angiogenesis, and STAT3 is associated with cancer pathogenesis." (PMID 35563301, 2022). "Due to its central contribution to several hallmarks of cancer and its association with poor clinical prognosis, STAT3 represents a promising therapeutic target for cancer therapy." (PMID 35865518, 2022). "ZIC5 activates signal transducer and activator of transcription 3 (STAT3), which is known to be associated with drug resistance in many types of cancers, by promoting anti‐apoptotic factors such as BCL‐XL." (PMID 36282887, 2022). "In various cancer types, STAT3 expression was observed to be abrogated specifically in myofibers, and ablation of STAT3 in myofibers prevented muscle loss through the UPS system." (PMID 36231065, 2022). "STAT3 is required for cell transformation mediated by the Src oncogene, directly linked to human cancers." (PMID 35113040, 2022). "Though, IPF shares a series of risk factors (ageing, smoking and environmental exposures), pathogenic pathways (PI3K-γ/AKT, JAK2/STAT3) and biological abnormalities (genetic and epigenetic alterations) with cancer." (PMID 35626663, 2022). "Evidence indicates that STAT-3 is highly phosphorylated and activated in many cancer cells, and its activation is closely linked to cancer cell survival." (PMID 35740967, 2022). "Aberrant activation of STAT3 in cancer cells causes the continuous transcription of cell growth factors and anti-apoptotic molecules that play a crucial role in maintaining cell growth and survival." (PMID 36144783, 2022). "Phosphorylated STAT3 dimers in cancer cells promote the transcription of genes associated with proliferation, cell cycle regulation, adhesion, metastasis and angiogenesis." (PMID 36700235, 2022). "In summary, STAT3 activity is critically implicated in determining the outcome of cancer immunity by orchestrating the release of immunomodulating cytokines." (PMID 35865518, 2022). "Curcumin decreased 5-fluorouracil resistance of gastric carcinoma by suppressing STAT3 in cancer associated fibroblasts." (PMID 36700235, 2022). "STAT3, a transcription factor known to be important in cancer cachexia, has been shown to be closely associated with abnormal activation of STAT3 in cancer cachexia, and supplementation with creatine also inhibited its phosphorylation." (PMID 36569317, 2022). "Meanwhile, several studies have demonstrated that CD44 linked with Stat3 contributed to cancer initiation and development." (PMID 36678534, 2022). "STAT3 is the most commonly concerned protein in solid cancers, and in numerous types of cancer patients, an excessive activity of STAT3 is associated with poor survival outcomes." (PMID 36558146, 2022).
cancer (continued). "Related studies have shown that STAT3 is associated with fat wasting and the acute phase response to cancer cachexia." (PMID 36091226, 2022). "One such mechanism is the persistent activation and mitochondrial translocation of STAT3, which is implicated in inflammatory pathologies and many types of cancers." (PMID 35928250, 2022). "For example, Signal transducer and activator of transcription 3 (STAT3) is a critical transcription factor and its hyperactivation is tightly associated with cancer initiation and progression." (PMID 35410300, 2022). "Conversely, NF-κB and JAK/STAT3 pathways also contribute to the production of IL-6, forming a cancer-associated NF-κB/IL-6/STAT3 positive feedback loop, making cancer a de facto chronic inflammatory disease." (PMID 35884974, 2022). "The signal transducer and activator of transcription (STAT3) signal is constitutively activated during cancer development and is associated with different hallmarks of cancer." (PMID 36010974, 2022). "Aberrant activation of STAT3 has been associated with cancer cell migration and cell cycle progression." (PMID 34561554, 2022). "The expression KRAB-STAT3 inhibits cancer cell proliferation both in vitro and in vivo, caused by inhibition of STAT3 signaling through KRAB-STAT3." (PMID 35810312, 2022). "The aberrant activation of the JAK2/STAT3 signalling pathway has been observed in many types of cancer, and it is closely associated with tumorigenesis, cell proliferation, angiogenesis and the migration of cancer cells." (PMID 35068042, 2022). "Signal transducer and activator of transcription 3 (STAT3) have been associated with the aggressive phenotype of cancer." (PMID 35189921, 2022). "Higher STAT3 activation is associated with increased risk of recurrence and shorter survival in different cancers." (PMID 35264191, 2022). "This “compensatory” JAK2/STAT3 activation is considered as one of the main causes of drug resistance of cancer cells to MAPK pathway-targeted drugs." (PMID 36430869, 2022). "Activation of STAT3 or STAT5 is typically associated with poor prognosis in cancers therefore development of effective cancer treatment focusing on suppression of STAT activity or inhibition of JAK/STAT pathway." (PMID 36339589, 2022). "The persistent activation of STAT3 denotes a major hallmark as far as malignant cancers are concerned." (PMID 36080130, 2022). "The JAK2/STAT3 pathway plays an important role in cell growth, proliferation and survival and has been associated with many human cancers 22-24." (PMID 35517401, 2022). "Loss of LXN in macrophage activates JAK1/STAT3/PD-L2 pathway, which contribute to the immune escape of cancer cells by attenuating the function of T cells in TME." (PMID 36323670, 2022). "STAT3 is a major transcription factor associated with tumorigenesis due to aberrant regulation in cancer cells; it is found to promote cell invasion, metastasis, and angiogenesis via regulation of related genes." (PMID 36339589, 2022). "We observed that accumulative evidence has demonstrated that the IL-6/JAK/STAT3 pathway is aberrantly hyperactivated in many types of cancer and such hyperactivation is generally associated with a poor clinical prognosis." (PMID 35756644, 2022). "Effects of hepcidin downregulation are explained, specifically, increased cancer proliferation via activation of CDK1/STAT3 pathway and increased HCC risk due to reduction in a hepcidin-mediated protective effect against hepatic stellate cell activation." (PMID 35264787, 2022). "Resveratrol also suppressed Sox2 expression and activated Akt and STAT3 that are induced by cancer-associated fibroblasts." (PMID 35566016, 2022). "STAT3 is aberrantly hyperactive in most malignant cancers, including CRC, and is generally associated with a poor clinical prognosis, suggesting that STAT3 is an important molecular target for CRC therapy." (PMID 35372504, 2022).